TNF (tumor necrosis factor)
Diseases named in the same sentence as TNF in open-access papers (continued):
Sharing a sentence is not in itself a finding about the gene and the disease.
tumor (continued). "This may explain why we observed a higher proportion of deaths from severe RA in the anti-TNF–treated group but a higher proportion of deaths from neoplasm, a relative contraindication for treatment, in the control group." (PMID 20662063, 2010). "However, the curative effect of TNFα has been undermined by the induced-NF-κB activation in many types of tumor." (PMID 20367887, 2010). "In addition to their role as inhibitors of the alternative NF-κB pathway, cIAPs also have important pro-survival functions downstream of TNF, and inhibition of cIAPs in many tumor cell types leads to apoptosis." (PMID 21151480, 2010). "In addition, several studies have shown a role for TNF-α-induced MMPs in tumour progression and invasiveness." (PMID 20126546, 2010). "The autocrine action of TNFα may have direct effects on tumor cell spread via acting on the chemokine receptor CXCR4 and also stimulation of blood vessel formation in the peritoneal tumor by inducing expression of VEGF and CXCL12." (PMID 21318181, 2010). "Although the TNF-α signal transduction pathway is complex and not fully understood, the pro-inflammatory effects of TNF-α are primarily because of its ability to activate NF-κB whereas the anti-tumor effects are due to activation of Caspase 3 and induction of apoptosis." (PMID 20087353, 2010). "The aim of this study was to determine whether MA potentiates the anti-tumor activity of TNFα though the regulation of NF-κB activation." (PMID 20367887, 2010). "However, we demonstrated that macrophages, TNFα and IL-1β increased the levels of Snail in tumor cells, a known Wnt target gene and regulator of tumor cell apoptosis." (PMID 20661477, 2010). "Therefore, inhibition of NF-κB activation by pharmacologic approaches has become an attractive strategy for improving the anti-tumor activity of TNFα." (PMID 20367887, 2010). "Thus, the relationship among PUFAs, eicosanoids and TNF-α and their actions on tumor cells is complex." (PMID 20932327, 2010). "However, emerging evidences have shown TNF-α was one of the major mediators of cancer-related inflammation and acted as a tumour-promoting factor." (PMID 20087353, 2010). "Furthermore, TNF-α enhances the invasiveness of tumour cells through induction of MMPs or α2β1 integrin." (PMID 20087353, 2010). "Also, Tumor Necrosis Factor-α (TNFα) produced in the tumor microenvironment can lend MM cells the ability to escape apoptosis by up regulating NF-κB dependent anti-apoptotic molecules." (PMID 20920357, 2010). "With H. pylori being a potent inducer of TNF-α, whether TNF-α, a tumor promoter, is involved in the induction of CXCR4 expression by H. pylori was also under research in this study." (PMID 20699000, 2010). "However, TNF has been shown in other experiments to promote proliferation, invasion, and metastasis of tumor cells." (PMID 20546618, 2010). "Second, thalidomide inhibits TNF-α release at the tumor site and reduces peripheral nociceptive inputs to reach the spinal cord, which may inhibit glial activation and subsequent spinal release of proinflammatory cytokines." (PMID 20923560, 2010). "A recent study has documented that versican, a large extracellular matrix proteoglycan, can activate tumour-infiltrating myeloid cells through TLR-2 and its coreceptors TLR-6 and CD14 and elicit the production of proinflammatory cytokines including TNF-alpha that enhance tumor metastasis." (PMID 20652007, 2010). "For example, TNF-α is an essential cytokine responsible for tumor promotion in mouse skin." (PMID 24281172, 2010). "Functional analysis showed that pathways controlling cell cycle, protein synthesis, matrix metalloproteinases, TNFα/NFkB, and inflammatory responses were up-regulated in tumours, while Krebs cycle, the electron transport chain, and fatty acid beta oxidation were down-regulated." (PMID 20459814, 2010).
tumor (continued). "Similarly, in our study, we found that intraperitoneal injection of TNF-α synthesis inhibitor thalidomide was effective in reducing tumor-induced mechanical allodynia and thermal hyperalgesia." (PMID 20923560, 2010). "The function of TNF-α as a key regulator of the tumour microenvironment is well recognised." (PMID 20087353, 2010). "Moreover, some cytokines (IL-2, IL-21 and TNF) and heparin can act as anti-tumor mediators, released by mast cells, limiting tumor progression." (PMID 20569458, 2010). "Nuclear factor-κB is critical for TNF-α-induced tumour promotion." (PMID 20087353, 2010). "Cytokines secreted by the activated tumor stroma modulate tumor growth and regulate their survival and invasiveness through activation of oncogenic signaling pathways in tumor cells, examples being activation of NF-κB by TNFα and IL-1β, and activation of STAT3 by IL-6." (PMID 20661477, 2010). "One outstanding question is whether the anti-tumor activity of the SMAC mimetics in vivo is also dependent on engagement of the TNFα pathway." (PMID 20067634, 2010). "Loss of an inhibitory effect of cAMP on p38 activation might help certain types of tumor cells escape from TNF-α-induced cell death." (PMID 20070884, 2010). "We found that the anti-tumor activity of liqi might also be related to its regulatory effects on IL-2 and TNF-α, both of which play important roles in cancer therapy." (PMID 19570195, 2009). "The low efficiency of tumor-colonization observed in patients might be due to an over-attenuation that might not only affect the induction of TNF-α but the inflammatory response in general." (PMID 19693266, 2009). "Depletion of TNF-α retarded blood influx and delayed bacterial tumor-colonization." (PMID 19693266, 2009). "Subsequent studies have shown that TNF-α can rapidly alter endothelial permeability and markedly decrease interstitial fluid pressure, both of which are believed to be critical for drug uptake in tumours." (PMID 19568235, 2009). "Among these, TNF-α is reported to be poorly expressed in TAMs and may be pro-apoptotic to tumor cells." (PMID 19696929, 2009). "These roles are supported by mouse models that implicate both NF-κB and TNF-α in tumor promotion." (PMID 19390683, 2009). "Once in the tumor, E. coli for instance altered the tumor microenvironment in murine breast tumors by vascular remodeling, focal concentration of tumor associated macrophages and focal expression of MMP-9 and TNF-α around bacterial colonies." (PMID 19693266, 2009). "Like VEGF, TNF can also be secreted by both mast cells and tumor cells." (PMID 23283207, 2009). "Our results are consistent with mouse models that implicate NF-κB and TNF-α in tumor promotion." (PMID 19390683, 2009). "The adhesion of tumor cells to the apical endothelial membrane resembles their interaction with leukocytes when endothelial cells have been activated with tumor necrosis factor (TNF)." (PMID 19930605, 2009). "In addition, TNF-α augments tumor remodeling with respect to tumor cell motility and tumor invasion via the induction of MMPs." (PMID 19924065, 2009). "The most notable change within the tumor microenvironment was an increase in TAM frequency over the course of tumor growth, which correlated with functional impairment, demonstrated by a decreased proportion of TNF-α-secreting cells after mitogenic stimulation of ex vivo TAMs." (PMID 19226468, 2009). "A synergistic anti-tumor effect has been observed when TNF-α is combined with IL-2." (PMID 19570195, 2009). "Inhibition of HO-1 reversed the inhibitory effect of IL-10 on TNFα production Therefore, inhibition of HO-1 in tumor tissues may increase TNFα production, hence increasing the inflammatory response of the host." (PMID 19508729, 2009). "However, depletion of TNF-α by antibodies had only a partial effect on blood influx and bacterial tumor-colonization." (PMID 19693266, 2009). "TNF has been shown to increase angiogenesis, tumor growth, and metastasis." (PMID 23283207, 2009).
tumor (continued). "Within this microenvironment, it may participate in a chemokine-driven vicious cycle where MCP-1 can be secreted by tumor cells which subsequently promotes the secretion of TNF-α as well as other promalignancy factors." (PMID 19192289, 2009). "Majority of tumor cells have been shown to be resistant to TNFα-mediated lysis." (PMID 19148288, 2009). "After establishing that RGD-A-TNF preferentially localizes within tumor vascular endothelium after systemic administration, we next evaluated whether vector localization would result in targeted TNFα gene expression." (PMID 19330034, 2009). "In parallel high concentrations of TNF-α could be found in blood and a tremendous influx of blood into the tumor was observed at that time." (PMID 19693266, 2009). "Indeed,some of the most prominent tumor-promoting mediators of macrophages—TNFα, MMP9, iNOS—are known to be repressed by PPARγ ligation." (PMID 18615187, 2008). "As TNF-α is secreted by resident macrophages and stromal cells following stimulation, the tumor cells under oxidative stress at 6 h DLI PDT could have enhanced the expression of TNF-α." (PMID 18549507, 2008). "Similar to the inhibition of angiogenic factors, curcumin has been shown to regulate proteins related to cell-cell adhesion, such as β-catenin, E-cadherin and APC and to inhibit the production of cytokines relevant to tumor growth, e.g. tumour necrosis factor-α (TNF-α) and interleukin-1." (PMID 18834508, 2008). "We assessed whether DCs prepared by RNA electroporation or pulsing with UV-irradiated tumor cells respond differently to maturation stimuli such as TNF-α and LPS." (PMID 18445282, 2008). "Also, TNF-α and reactive nitrogen intermediates play major roles in the in vitro anti-tumor activity of mouse peritoneal exudates from mice stimulated with wall peptidoglycan from B. infantis." (PMID 18950540, 2008). "Moreover, in order to mimic the real physiological situation of tumor metastasis, tumor cell transmigration across HUVEC monolayers pre-activated by TNF-α should be also measured under flow condition." (PMID 18350162, 2008). "Furthermore, the cytokines IL-2, IL-4, TNFα and IFNγ have been shown to inhibit tumor-induced angiogenesis in some animal models by inhibition of tumor stroma formation." (PMID 19578507, 2008). "Additionally, the butanol extract of B. adolescentis SPM0212 induced macrophage activation and significantly increased the production of TNF-α and NO, which regulate immune modulation and are cytotoxic to tumor cells." (PMID 18950540, 2008). "In parallel with the induction of tumor cell immunogenicity, UV-irradiation made tumor cells more sensitive to natural killer cell-mediated cytotoxicity and to lysis by TNF, suggesting that immunogenicity and TNF sensitivity are two independent UV-induced properties." (PMID 18439316, 2008). "Tumor Necrosis Factor (TNF) family members (19 ligands and 29 receptors) represent a pleiotropic family of agents, related to a plethora of cellular events from proliferation and differentiation to apoptosis and tumor reduction." (PMID 18366696, 2008). "The antitumoral effects of TNF-α have been shown to be the result of three different biological mechanisms: primarily hemorrhagic necrosis by TNF-α action on tumor endothelium, TNF-α immunomodulatory activity on immune effector cells, and a direct TNF-α mediated cytotoxic effect on tumor cells." (PMID 18257926, 2008). "In tumour homogenates mean basal values of TNFα were: 255.0 ± 30.0 pg/mg of protein (n = 20), at 30 min 210.0 ± 12.5 pg/mg of protein (n = 18), P = 0.20; at 60 min 200.0 ± 15.0 pg/mg of protein (n = 18), P < 0.05; and at 90 min 210.0 ± 15.0 pg/mg of protein (n = 18), P = 0.10." (PMID 18045456, 2007). "However, several cytokines produced by monocytes (IL-1β, IL-6 and MCP-1) or macrophages (such as IL-1β, IL-6, IL-8, MIP-1β and TNF-α) are highly expressed by the tumour." (PMID 17261184, 2007).
tumor (continued). "In the experimental setting, TNFα acts as a tumourigenic agent and tumour promoter." (PMID 17968426, 2007). "Tumor necrosis factor- alpha (TNF-α) induces apoptosis of a variety of tumor cell types." (PMID 23675041, 2007). "Since TNFα is involved in host defense and tumor surveillance, there have been concerns that anti-TNFα therapy might lead to adverse events, particularly infection and malignancy." (PMID 17763441, 2007). "However goserelin administration achieves regression in tumour development associated to inhibition PRL, TNF alpha and NO expression." (PMID 18045456, 2007). "Activation of endogenous NF-kB factors by TNF-α also induces DR5 expression in tumor cells." (PMID 17592646, 2007). "In addition, TNF has been shown to mediate carcinogenesis through induction of proliferation, invasion, and metastasis of tumor cells." (PMID 16438713, 2006). "In addition, we showed that in patients with osteolysis the activation of osteoclastic precursors depends on circulating tumor cells or on factors released from the tumor site, such as TNF-α." (PMID 17205128, 2006). "In tumor cells, TNFα expression can promote proliferation and inhibit apoptosis, suggesting that increased TNF transcription in BT.siMUC1 could contribute to the increased proliferation seen in these cells." (PMID 16846534, 2006). "However, extensive research during past years has made it apparent that TNF-α enhances the incidence of metastasis in several tumour models." (PMID 15841081, 2005). "Thus, in certain cancers TNF has been shown to induce haemorrhagic necrosis of tumours, whereas in others it has been shown to promote cancer." (PMID 15026813, 2004). "Similarly, tumour cell lines infected with a retrovirus carrying the TNF gene augmented metastatic activity of the tumour." (PMID 15026813, 2004). "Since the mithramycin/TNF combination is capable of inducing apoptosis in TF-1 cells independently of the mitochondrial pathway, combining TNF treatment with mithramycin could have potential for elimination of tumour cells that express large amounts of Bcl-2." (PMID 15138489, 2004). "Support for this hypothesis is provided by experiments where Colon 38 tumours were implanted in TNF−/− and TNFR−/− knockout mice, where the antitumour effects following administration of the same dose of DMXAA are substantially reduced." (PMID 14970872, 2004). "Prior to this, we ensured that blocking TNF by a known mechanism, monoclonal antibodies to TNF, could also reduce tumour metastasis." (PMID 15026813, 2004). "Although some of those differences were only minor, they are in line with previous studies which demonstrated much higher resistance of metastatic OSCC lines to TRAIL-induced cell death and also to TNF-α-induced apoptosis than their corresponding primary tumor lines." (PMID 15613236, 2004). "Based on our findings in the ILP studies, it is indicated to study whether TNF-α can improve tumour response in different tumours after IHP and, if so, to investigate the capability of TNF-α to augment drug accumulation in this perfusion setting." (PMID 12610519, 2003). "The effect of TNF-α on the growth of tumour cells in vitro was determined to evaluate whether the synergistic effect of TNF-α could be related to direct tumour cell toxicity." (PMID 12610519, 2003). "However, in the presence of the BAb, the curve for group 7 was shown to be statistically different from the growth curves for tumours treated with RT alone or RT+TNFα (P=0.0011)." (PMID 14612914, 2003). "However, in the present study, we demonstrated that TNF-α is effective in increasing vascular permeability for melphalan selectively in tumour tissue." (PMID 12610519, 2003). "While avoiding the systemic side effects of TNFα, this method involves injections in or near the tumour, which might be difficult to perform in the case of pelvic or retroperitoneal tumours." (PMID 14612914, 2003).
tumor (continued). "Furthermore, TNFα was implicated as a major factor in FAA-induced vascular shutdown, and the haemorrhagic necrosis seen in subcutaneously transplanted tumours treated with FAA had already been likened to effects seen after TNFα treatment." (PMID 12888809, 2003). "The central objective of this study was to test the hypothesis of whether increased expression levels of Cath-L or Cath-B would enhance the sensitivity of tumour cells to TNF-mediated apoptosis." (PMID 14562034, 2003). "We already hypothesised that TNF-α by increasing leakage of tumour vessels enhances intratumoural concentrations of chemotherapeutics." (PMID 12610519, 2003). "Patients with the TNF+488A or TNF−859T were more likely to present with a moderately differentiated tumour than those patients without the uncommon allele." (PMID 12966432, 2003). "With TNF-α alone, at the most some tumour growth was observed." (PMID 12610519, 2003). "Over 10 years ago, it was hypothesised that TNFα could increase tumour response to radiation through stimulation of the host antitumour immune responses, direct tumour-cell kill, or through the increase in tumour-cell sensitivity to radiation." (PMID 14612914, 2003). "The increased TNFα secretion in RCC patients may be considered as a favourable compensatory mechanism to counteract tumour growth." (PMID 11986770, 2002). "Perfusions with 40 μg melphalan and 50 μg TNF resulted also in major tumour shrinkage." (PMID 11953868, 2002). "The TNF response in tumour tissue was considerably higher than that in serum." (PMID 12177785, 2002). "One day after perfusion with TNF alone haemorrhagic necrosis in tumour was observed." (PMID 11953868, 2002). "Toxicity of TNF-α is also known to be highly dependent on tumour cell oxygenation status." (PMID 11875711, 2002). "In this report, we demonstrated that apoptosis induced by 7-ethyl-10-hydroxycamptothecin, tumour necrosis factor-α (TNF-α) or interleukin (IL)-2-activated natural killer (NK) cells was significantly inhibited in tumour cells transduced with the SCC Ag-1 cDNA, as compared to control cells in vitro." (PMID 10732775, 2000). "Co-administration of thalidomide may represent a novel approach to improving selective intra-tumoural TNF-α production and anti-tumour efficacy of DMXAA." (PMID 10360649, 1999). "TNF-alpha immunoreactivity was also compared with various important tumour variables known to relate to outcome in this disease (microvessel density, node status, grade, stage, receptor status and macrophage infiltration), as well as relapse-free and overall survival data for these patients." (PMID 9649140, 1998). "In this study we determined the level of tumour necrosis factor alpha (TNF-alpha) in liver and tumour tissue samples obtained from patients with colorectal metastases confined to the liver, who were treated with isolated liver perfusion with TNF-alpha and melphalan." (PMID 9166943, 1997). "Furthermore, we demonstrated that the level of TNF-alpha in the liver tissue samples was about seven to eight times higher than in tumour tissue." (PMID 9166943, 1997). "In tumour tissue, a significant TNF-alpha increase was observed in one out of five patients." (PMID 9166943, 1997). "In conclusion, our findings suggest that the enhanced anti-tumour effect after the combination of TNF-alpha with melphalan results from potentiation of the TNF-alpha-induced vascular changes accompanied by increased vascular permeability and platelet aggregation." (PMID 8980389, 1996). "These hybrid TNF-alpha s showed over ten times greater anti-tumour effects than native TNF-alpha." (PMID 8855980, 1996). "Thus, the molecular size, which was determined by the degree of PEG modification and PEG molecular weight, influences the specific activity and anti-tumour effects of hybrid TNF-alpha." (PMID 8855980, 1996). "Optimal PEG modification of TNF-alpha markedly increased its bioavailability and may facilitate its potential anti-tumour therapeutic use." (PMID 7734321, 1995).